DPEP2NB (DPEP2 neighbor)
Gene: Protein-coding gene on chromosome 16 (68,013,436 to 68,015,911, reverse strand). Ensembl gene ENSG00000263201.
Gene Ontology:
Molecular function: protein binding
Genetic constraint (gnomAD): Loss-of-function variants: 1 observed, 1.29 expected, observed/expected ratio (o/e) 0.78, 90% interval 0.23 to 1.86. That is too few expected variants to judge how well the gene tolerates losing a copy. Missense variants: 104 observed, 114.35 expected, observed/expected ratio (o/e) 0.91, 90% interval 0.77 to 1.07. Synonymous variants: 31 observed, 44.78 expected, observed/expected ratio (o/e) 0.69, 90% interval 0.52 to 0.93.
Homologues: Orthologues: chimpanzee DPEP2NB (99% identical), macaque DPEP2NB (92% identical), pig DPEP2NB (83% identical), rat Dpep2nb (61% identical), mouse Dpep2nb (58% identical), rabbit DPEP2NB (55% identical).